PARP1 (poly(ADP-ribose) polymerase 1)
Diseases named in the same sentence as PARP1 in open-access papers (continued):
Sharing a sentence is not in itself a finding about the gene and the disease.
breast cancer (continued). "A comprehensive analysis of the PARP-1/BRCA1/53BP1 factors of DNA repair in the different breast cancer subtypes could enable this selection and promote the use of these compounds outside the TN subtype." (PMID 24191908, 2013). "Of note is that several studies suggest that PARP1 inhibitors may also be beneficial in other subtypes of breast cancer beyond TNBC." (PMID 20979652, 2010). "Veliparib (ABT-888) is another PARP1 inhibitor being evaluated in breast cancer." (PMID 20979652, 2010). "Whether using a PARP1 inhibitor will lead to synthetic lethality in other breast cancer subtypes is an intriguing question that is worth exploring." (PMID 20979652, 2010). "PARP1 has been implicated in the repair of DNA damaged by estradiol in human estrogen-receptor-negative (ER-/-) breast cancer cells." (PMID 19961617, 2009). "Thus, the apoptosis of human ER -/breast cancer cells was prevented by TCDD-induced activation of PARP1 and aided the survival of these cancer cells." (PMID 19961617, 2009). "Therefore, p-Y158 PARP1 could be a better biomarker in predicting FGFR3-mediated PARPi resistance than p-FGFR in breast cancer tissues." (PMID 40460005, 2025). "Thus, PRMT6 expression was positively correlated with that of PARP1 in breast cancer samples." (PMID 36941223, 2023). "In addition, PARP1 was highly expressed in breast cancer samples included in the GEPIA database." (PMID 38037159, 2023). "For example, PARP1 promotes the repair of ssDNA breaks, which, unless repaired, can become DSBs, and PARP inhibitors therefore selectively target cancer cells with defective DSB repair ability and have thus been used to treat breast cancer patients carrying BRCA1 or 2 mutations." (PMID 37009801, 2023). "Whether PARP1 drives CDK4/6i resistance in breast cancer is worth further study." (PMID 38037159, 2023). "DDR-targeted therapies are emerging as promising strategies for treating breast cancer, particularly triple-negative breast cancer, wherein overexpression of DNA repair proteins, such as PARP1 and replication protein A, might alter the sensitivity to chemotherapy and DDR inhibitors." (PMID 37448962, 2023). "In addition to double-strand break repair, BRCA2 (breast cancer 2) is also closely related to homologous recombination repair, while PARP-1 (poly (ADP-ribose) polymerase 1) plays important regulatory roles in single-strand break repair and basic cleavage repair." (PMID 38006403, 2023). "Furthermore, Abemaciclib treatment led to PARP1 elevation in 3 breast cancer cell lines." (PMID 38037159, 2023). "Based on our study, we propose the co-targeting of ERα, PI3Kα, p21, and PARP1 activities as a potentially efficient and safe strategy for blocking multiple cell survival avenues, reducing the emergence of resistance, and eventually leading to the selective death of ERα + breast cancer cells." (PMID 36869202, 2023). "In addition, snoRNA73A, snoRNA73B, and snoRNA74A can activate poly [ADP-ribose] polymerase (PARP-1) to regulate downstream signaling pathways and participate in breast cancer development by combining with the DNA repair enzyme PARP-1 in the absence of DNA damage stimulation." (PMID 35790714, 2022). "Poly (ADP-ribose) polymerase 1 (PARP1) has high therapeutic value as biomolecular target for research and development of small molecules with antineoplastic activity, since it is upregulated in many cancers, especially in ovarian and BRCA 1/2 mutated breast cancers." (PMID 36094927, 2022). "PARP-1 can also recruit protein MRE11, ATM (ataxiatel angiectasia mutated) to suppress the transcription factors E2F4 and P130 complexes and impact the expression of breast cancer susceptibility genes BRCA1 and RAD5, which transiently protects the DNA gaps and inhibits recombinant." (PMID 36590386, 2022).
breast cancer (continued). "PARP1/2 inhibitors (PARPis) are the first class of drugs acting by the principle of synthetic lethality that have been approved for clinical use for the treatment of homologous recombination (HR)-deficient types of cancer (mainly, BRCA1/2-deficient ovarian and breast cancers)." (PMID 34572428, 2021). "A potential relevance of PARP-1 inhibition in ER+ breast cancers might emerge from our functional analyses of a new single nucleotide variant (SNV) within the aromatase promoter I.3/II-region (SNV(T-241C); NC_000015.10:n.51243270T>C; GRCh38.p13 human genome reference)." (PMID 32059481, 2020). "Next, we investigated whether the PARP1 function is essential for breast cancer cells." (PMID 32455851, 2020). "Therefore, ZINC20032678 could target both c-Met/PARP-1 sequentially activating the downstream apoptotic signaling pathway, eventually inducing breast cancer cell apoptosis." (PMID 32201536, 2020). "Therefore, ZINC20032678 could be considered as a promising and effective c-Met/PARP-1 inhibitor in future breast cancer drug discovery." (PMID 32201536, 2020). "Interestingly, previous studies have also indicated that c-Met associated with and phosphorylated PARP-1 at Tyr907, and targeting both t c-Met and PARP-1 could synergize to suppress the growth of breast cancer cells both in vitro and in vivo." (PMID 32201536, 2020). "However, whether H19 takes part in the dysregulation of PARP1 expression in breast cancer cells remains unknown." (PMID 32345117, 2020). "In protein expression, PARP1 (OR 1.147, 95% CI 1.067 ~ 1.233, P < 0.05), XRCC4 (OR 1.088, 95% CI 1.015 ~ 1.166, P < 0.05), XRCC1 (OR 1.114, 95% CI 1.021 ~ 1.215, P < 0.05), ERCC1 (OR 1.068, 95% CI 1.000 ~ 1.141, P < 0.10) were risk factors for postoperative metastasis of breast cancer." (PMID 33184404, 2020). "Thus, low doses of PARP-1 inhibitors might be potentially useful for estrogen-deprivation of ER+ breast cancers." (PMID 32059481, 2020). "PARP1 plays a crucial role in multiple biological processes and PARP1 activation contributes to the development of various inflammatory and malignant disorders, including lung inflammatory disorders, cardiovascular disease, ovarian cancer, breast cancer, and diabetes." (PMID 31500199, 2019). "Almost 20 years later, the poly (ADP-ribose) polymerase 1 (PARP1) inhibitor (PARPi) olaparib became the first synthetic lethality-based treatment approved by the Food and Drug Administration (FDA) as a single-agent therapy for BRCA-deficient ovarian and breast cancer patients." (PMID 31615159, 2019). "Additionally, PARP-1 protein is higher in TNBC specimens than in non-TNBC breast cancers, and high PARP-1 expression is associated with worse PFS in TNBC." (PMID 31877876, 2019). "However, it is also known that both ovarian and breast cancers may rely crucially on induction of activity of poly (ADPribose)polymerase-1 (PARP-1), which appears to play a crucial role in myocardial energy impairment in a rat model of TTS." (PMID 32154026, 2019). "Additionally, PARP‐1 protein is higher in triple negative breast cancer (TNBC) specimens than in non‐TNBC breast cancers, and high PARP‐1 expression is associated with worse PFS in TNBC." (PMID 30467127, 2018). "In this study, we evaluated NHERF1, BRCA1 and PARP1 protein expression by means of immuno-histochemistry in a retrospective series of invasive BC including a subgroup of triple negative breast cancers (TNBCs)." (PMID 29029467, 2017). "Therefore, the assessment of PARP1 expression in tumor samples may improve the selection of breast cancer patients for PARP inhibitor therapy." (PMID 29212245, 2017). "Consequently, targeting PARP1 and inhibiting its relevant biological function may be another avenue of breast cancer therapy, especially for TNBC." (PMID 28442756, 2016).
breast cancer (continued). "In addition, Immunohistochemistry study with breast cancer tissues also indicated that elevated PARP1 expression and pathology grade at diagnosis to PARP1 expression was different, which indicated the concordance of PARP1 status between serum and tumor tissue in breast cancer." (PMID 25865228, 2015). "Cancers defective in DNA repair, specifically cancers with mutations in the breast cancer associated BRCA1 and BRCA2 genes and triple-negative breast cancer (which shares molecular and pathologic features with BRCA1-related breast cancers) appear to be particularly sensitive to inhibition of PARP-1." (PMID 22619725, 2012). "Another clue that PARP1 inhibition might be beneficial in other breast cancer subtypes relates to its relationship with phosphatase and tensin homolog (PTEN), a phosphatase that contributes to the regulation of cell cycle progression, cell proliferation and DNA repair." (PMID 20979652, 2010). "Elevated BAX expression and PARP-1 cleavage in MCF-7 and MDA-MB-231 breast cancer cells treated with nanoencapsulated PTX indicate that apoptosis is the primary mechanism of cell death, regardless of the nanocarrier type." (PMID 41790974, 2026). "Niraparib is a potent oral, selective PARP-1 and PARP-2 inhibitor that has shown promising clinical activity in patients with advanced ovarian and breast cancer." (PMID 40507226, 2025). "Key genes in the parthanatos pathway, such as PARP1, PTEN, and AIFM1, are critical drivers of breast cancer initiation, progression, drug resistance, and metastasis." (PMID 40564403, 2025). "We characterize alterations in PARP1, delineate effects on DNA damage ADPr signaling, and identify other changes in Olaparib-resistant BRCA1/2 mutant breast cancer cells." (PMID 40669753, 2025). "Notably, a recent study reported that in BRCA-mutant breast cancers, PARP1 amplifications occur significantly more frequently in post-treatment recurrent lesions than in primary tumors, suggesting that PARP1 amplifications may contribute to post-treatment recurrence in BRCA-mutant breast cancer." (PMID 40564403, 2025). "We have also demonstrated that salubrinal inhibits DNA repair in breast cancer cells and that, like salubrinal, raphin‐1 decreases PED‐DHGG survival, induces DNA damage, and enhances DNA damage in the presence of the PARP‐1 inhibitor niraparib." (PMID 40632659, 2025). "Its therapeutic relevance is compounded in breast cancer, particularly in BRCA1 or BRCA2 mutant cancers, where compromised homologous recombination repair (HRR) leaves a synthetic lethal dependency on PARP1-mediated repair." (PMID 41304924, 2025). "Taken together, PARP1 > 6, p50 > 2, and TNF-α > 4 have a certain value in predicting breast cancer metastasis, and the predictive value is better when they are combined for diagnosis (Secombine = 97.94%, Spcombine = 71.13%)." (PMID 38388665, 2024). "Herein, we discovered novel small molecule inhibitors that simultaneously target PARP1 and NRP1 using structure-based virtual screening for the treatment of breast cancer." (PMID 39679370, 2024). "In melanoma and breast cancer senescent cells, the SASP was driven by the PARP-1/ NF-κB signalling cascade." (PMID 39201718, 2024). "We previously discovered one such mechanism in breast cancer involving DDX21, an RNA helicase that localizes to the nucleoli of cells and is a target of PARP1." (PMID 38767454, 2024). "The results showed that PARP1 and HDAC1 were markedly overexpressed in human breast cancers relative to healthy tissues, especially in TNBC." (PMID 38182579, 2024). "First, we confirmed the interaction between PARP1 and NPM1 protein in ESCC cells, which is consistent with previous findings in breast cancer cells." (PMID 39367700, 2024). "In 2018, the Rao group pioneered the development of a PROTAC molecule, designated as compound 3, which was shown to induce PARP1 cleavage and cell apoptosis in the MDA-MB-231 breast cancer cell line." (PMID 39695097, 2024).
breast cancer (continued). "PARP1 > 6, p50 > 2, and TNF-α > 4 have a certain predictive effect on breast cancer metastasis, and the predictive effect is better when they are combined in diagnosis." (PMID 38388665, 2024). "We also demonstrate that, as in breast cancer, OTI-611 traps CHD1L, PARP1, and PARP2 onto chromatin." (PMID 39684869, 2024). "Elevated PARP1, or reduced PER3 levels, were correlated with poor overall survival in breast cancer patients." (PMID 36941223, 2023). "NPM1 has been reported to epigenetically regulate PD-L1 expression in breast cancer, and once bound to poly (ADP-ribose) polymerase-1 (PARP1), NPM1 loses the ability to activate PD-L1." (PMID 37875480, 2023). "The selective and potent PARP-1 inhibitor AZD5305 also has PARP-1-DNA trapper activity, shown in a preclinical in vivo patient-derived xenograft (PDX) model of BRCA mutant breast cancer (HBCx-17)." (PMID 37351512, 2023). "The current study results indicate that PRMT6 binds to PARP1, recruiting the CRL4B complex which, together, stimulate histone methylation and ubiquitination modification, thereby promoting breast cancer progression." (PMID 36941223, 2023). "PARP1 catalyzes PARylation of BRD7 and enhances its degradation via the ubiquitin-proteasome pathway, resulting in resistance to chemotherapy in breast cancer cells." (PMID 36909172, 2023). "Disrupting DNA repair using PARP1/2 inhibitors (here forth referred to as PARP inhibitors) to induce cell death is a well-studied therapeutic approach, particularly for breast cancer." (PMID 37020198, 2023). "ETS1 is reported to up-regulate PARP1 in Ewing sarcoma and ovarian cancer, while ETS1 and ETS2 repress BRCA1 in breast cancer." (PMID 36814284, 2023). "Analysis of online datasets further revealed augmented PRMT6, PARP1, CUL4B, and DDB1 levels in breast cancer tissues compared with normal tissues." (PMID 36941223, 2023). "Thus, high PARP1 protein levels may be related to CDK4/6i resistance in breast cancer." (PMID 38037159, 2023). "Here, we reported that PARP1 was amplified in breast cancer cells and CDK4/6i-resistant patients, and knockdown or inhibition of PARP1 reversed drug resistance in cell experiments and animal models." (PMID 38037159, 2023). "We concluded that the PRMT6/PARP1/Cullin4B (CUL4B)‐Ring E3 ligase (CRL4B) complex transcriptionally represses PER3 and promotes breast cancer proliferation, invasion, and metastasis." (PMID 36941223, 2023). "We also validated the co‐expression of PARP1, PRMT6, and PER3 in normal breast tissue and three different grades breast cancer tissues using immunofluorescent staining (IF)." (PMID 36941223, 2023). "Preclinical work in hepatocellular carcinoma and breast cancer reveal that interactions between c-MET and EGFR result in the phosphorylation of PARP1 to mediate resistance." (PMID 37430137, 2023). "Olaparib is a United States Food and Drug Administration (FDA)-approved dual inhibitor of poly [ADP-ribose] polymerase 1 (PARP-1) and PARP-2 for the treatment of advanced ovarian and breast cancers." (PMID 38260135, 2023). "For the moment, PARP-1 inhibition shows strong effects on ETS-expressing cells from prostatic, breast carcinomas and Ewing’s sarcoma cell lines." (PMID 37686260, 2023). "In this study, the proliferation inhibition and apoptosis-inducing effects of PARP1 inhibitors in TNBC breast cancer cells and in vivo xenograft animal models were examined to investigate the molecular role of APE1 in PARP1-targeted therapy." (PMID 35463096, 2022). "In a panel of breast cancer cell lines, [18F]FTT uptake was compared in BRCA-mutant HCC1937 (high PARP1 expression) to the BRCA-wildtype MDA-MB-231 and MCF-7 cells and corresponded to these different expression levels." (PMID 35267438, 2022). "Among the genes in module 1, we found PARP1 and E2F1, recently discovered important genes for endocrine resistance in breast cancer, supporting the validity of our approach." (PMID 35401937, 2022).
breast cancer (continued). "For instance, PARP1 inhibitors (olaparib, rucaparib, niraparib, and talazoparib) are approved by the Food and Drug Administration (FDA) for clinical use in ovarian or breast cancer, and the variety of treated tumors is growing." (PMID 35806303, 2022). "At present, some studies have shown that PARP1 inhibitors can significantly prolong the PFS and OS of patients with epithelial ovarian cancer and breast cancer." (PMID 35875162, 2022). "We initially observed that PARP1 amplifications were statistically significant (90% CI per GISTIC) in recurrent tumors and observed most frequently (78%) in breast cancer recurrences." (PMID 36344544, 2022). "A novel PARP1 inhibitor, OL-1, was found to induce cell death and to inhibit cell migration in BRCA1 mutant MDA-MB-436 breast cancer cells." (PMID 34639169, 2021). "Together, the in vitro and in vivo evidence lead us to conclude that ICMT suppression in breast cancer cells creates a “BRCA-like” state, hence sensitizing them to PARP1 inhibitor–induced growth inhibition and apoptosis." (PMID 34610973, 2021). "In contrast, capsaicin-induced autophagy was reported to play important roles in the DNA damage responses of breast cancer cells, activating the ATM-DNA-PKcs-PARP-1 axis to protect cells against apoptosis." (PMID 34512323, 2021). "A previous study demonstrated that a higher expression of PARP-1, BRCA 1, and BRCA2 resulted in a shorter OS at 10 years in patients with breast cancer." (PMID 34830749, 2021). "In order to gain more insight into the mechanism of PARP1 and NUDT5 activation in breast cancer cells, a more comprehensive analysis of the phosphorylation events and signaling cascades is required." (PMID 33668737, 2021). "Taken together, our study showed that the CT gene, MEIOB, promoted breast cancer cell viability and mediated HRD by activating the PARP1-dependent DNA damage response." (PMID 33628586, 2021). "Therefore, we wanted to test whether, in breast cancer p65 interacts with PARP1." (PMID 32455851, 2020). "The IHC scores of PARP1, XRCC4 and ERCC1 were higher than that of 6, 6 and 3 breast cancer metastasis, respectively." (PMID 33184404, 2020). "The results showed that PARP1, GAPDH, and FOS protein were less expressed in normal breast tissues but were moderately expressed in breast cancer tissues." (PMID 32649310, 2020). "In addition, some authors have concluded that PARP-1 inhibition could be useful in a broader range of breast cancers, including ER+ breast cancers (not necessarily mutated in the BRCA DNA repair associated genes)." (PMID 32059481, 2020). "Breast cancers, particularly TNBCs, show upregulation of CCL2 and overall PARylation with positive feedback controlling CCL2 expression and PARP1 activity." (PMID 32455851, 2020). "So we combined protein expression (IHC score) of PARP1, XRCC4 and ERCC1 to detect the prognosis of breast cancer." (PMID 33184404, 2020). "Taken together, these results indicate that PARP-1, H1, and SIRT-1 directly interact in an aromatase promoter I.3/II-region crucial for the induction in BAFs in the vicinity of breast cancer cells in vivo." (PMID 32059481, 2020). "PARP1, XRCC4, ERCC1 is also found to be an independent factor for postoperative metastasis of breast cancer." (PMID 33184404, 2020). "Thus, we speculated that PARP1 is involved in chemotherapy response in breast cancer." (PMID 32345117, 2020).